VEGFA (vascular endothelial growth factor A)
Diseases named in the same sentence as VEGFA in open-access papers (continued):
Sharing a sentence is not in itself a finding about the gene and the disease.
metastatic disease (128 papers, 2002 to 2025). "These pertain to the WNT pathway and VEGFA signalling as potential drivers of metastatic disease, and possibilities to interfere with those pathways." (PMID 41168392, 2025). "In both situations, the HIF1-α gene moves to the cell nucleus, promoting VEGFA and PDGFa transcription, As a result many drugs targeting angiogenesis have been developed and are currently being used to treat metastatic disease." (PMID 29202733, 2017). "Despite elevations in VEGFA in metastatic disease, most VEGF inhibitors have failed clinical trials in metastatic CRPC." (PMID 26341082, 2015). "Our analysis of previously published gene expression data in this study revealed increases in VEGFA expression only in metastatic tumor samples; VEGFA expression in primary tumors was actually decreased." (PMID 26341082, 2015). "Interestingly enough, both NICD3 protein and VEGFA transcripts were found to be upregulated in the metastatic tumors compared to the corresponding paired primary tumors of HGSOC patients." (PMID 35884426, 2022). "However, five patients showed increased VEGFA gene expression in metastatic tumors compared with their primary, which also showed enhanced NICD3 expression as determined by IHC." (PMID 35884426, 2022). "Finally, to assess our findings in HGSOC patient population, we measured CDKN1A and VEGFA transcripts levels from primary and corresponding metastatic tumor tissues." (PMID 35884426, 2022). "Overexpression of VEGFA has been shown to correlate with metastatic tumor spread of MCC." (PMID 35892849, 2022). "Our analysis of gene expression data across normal prostate, primary prostate tissue, and metastatic prostate tumors revealed that while class 3 Semaphorin expression was reduced in both primary and metastatic tumors, VEGFA expression was elevated only in metastatic tumors." (PMID 26341082, 2015). "There are also a subset of metastatic tumors predicted to have low VEGFA-VEGFR2 signaling." (PMID 26341082, 2015). "We found six genes such as SPP1, VEGFA, POSTN, RUNX2, CD44, and FOXO1 that were consistently overexpressed in patients with bone metastasis compared to non-metastatic tumors." (PMID 36424413, 2022). "The highest differentially expressed genes in metastatic (MET and PRI+) versus non-metastatic tumors (PRI-) and SES included PLAU, PLAUR, MMP1, MMP10, MMP13, ITGA5, VEGFA, and various inflammatory cytokine genes." (PMID 35480116, 2022). "We found that the expression profile of the prognostic marker genes: CA9, VEGFA, and FN1, observed in in vivo orthotopic and metastatic tumor datasets was similar to the patient tumor datasets, whereas FN1 was only upregulated in the in vitro cell culture dataset." (PMID 40241258, 2025). "VEGFA levels were higher in the metastatic tumors compared to the non-metastatic ones; however, the difference was not statistically significant." (PMID 22895562, 2012). "However, this is not true of all metastatic tumors; a minority of patients with high VEGFA-VEGFR-2 also have high Sema3-NRP-PlxnA, possibly negating any clinical benefit of an anti-VEGFA agent." (PMID 26341082, 2015). "While MYC amplification was an acquired molecular event (included in the NGS panel used for the initial and metastatic tumor), it is not clear whether HSP90AB1, VEGFA, or GRIN2A were present at the time of initial diagnosis." (PMID 38837109, 2024).
endometrial cancer (125 papers, 2002 to 2026). Primary or metastatic malignant neoplasm involving the endometrium (mucous membrane that lines the endometrial cavity). "Therefore, the suppressive effects of VEGFA on endometrial carcinoma cell growth and metastasis might be caused by miR-34b-mediated decrease in VEGFA." (PMID 34703899, 2021). "The negative regulation of angiogenesis and tumor growth in endometrial cancer (EC) by downregulating vascular endothelial growth factor A (VEGFA) was also observed with miR-29b-3p." (PMID 39001478, 2024). "It was demonstrated that upon LGALS3BP overexpression, the PI3K/AKT/VEGFA signaling pathway was activated, significantly promoting the proliferation and migration of endometrial cancer cells." (PMID 39434140, 2024). "Bevacizumab (Avastin®, Genentech) is a recombinant humanized antibody against vascular endothelial growth factor-A (VEGF-A), and it has been studied as a single agent in women with recurrent endometrial cancer in study protocol GOG-229E." (PMID 34358108, 2021). "Another group discovered that miR-320a in extracellular vesicles (EVs) distorts endometrial cancer by disrupting the HIF1α/VEGFA signaling pathway." (PMID 35201481, 2021). "VEGFA was upregualted in patients with endometrial cancer, and functions as a proangiogenic factor in endometrial carcinoma." (PMID 34703899, 2021). "miR-34b also bind to and negatively regulate expression of vascular endothelial growth factor A (VEGFA) in endometrial carcinoma cells." (PMID 34703899, 2021). "ZFAS1 functioned as a miR-34b sponge to promote the cell growth and metastasis of endometrial carcinoma through upregulation of VEGFA." (PMID 34703899, 2021). "The increased cell apoptosis of HEC-1B induced by silence of ZFAS1 was restored by inhibition of miR-34b, revealing that silence of ZFAS1 suppressed endometrial carcinoma cell growth and metastasis through increase in miR-34b and decrease in VEGFA." (PMID 34703899, 2021). "Our results also showed that ZFAS1 enhanced expression of VEGFA in endometrial carcinoma cells through decrease in miR-34b." (PMID 34703899, 2021). "In conclusion, lncRNA ZFAS1 functioned as an oncogene to promote endometrial carcinoma cell proliferation and metastasis through miR-34b/VEGFA axis." (PMID 34703899, 2021). "Consistent with our work, downregulation of VEGFA was shown to restrain cell proliferation and migration as well as facilitate cell apoptosis of endometrial cancer cells." (PMID 32983957, 2020). "EGCG exhibits strong hypomethylating potential and also inhibits tumor angiogenesis in xenograft models through down-regulation of vascular endothelial growth factor A (VEGFA) and hypoxia inducible factor 1 alpha (HIF1α) in endometrial cancer." (PMID 30103412, 2018). "We test the correlation between miRNAs and VEGFA, we choose another 20 endometrial carcinoma tissues." (PMID 28404901, 2017). "To test the correlation between lncRNA-TUG1 and VEGFA, we choose another 30 endometrial carcinoma tissues." (PMID 28404901, 2017). "For endorsement of re-profiling of our findings to endometrial cancer, a VEGFA inhibitor, bevacizumab, was shown to be well tolerated and active in recurrent or persistent endometrial cancer based on progression-free survival at 6 months." (PMID 26716509, 2016). "Another study observed that exosomal miR-320a, derived from CAFs, has lower expression in endometrial cancer cells and tissues: it targets hypoxia-inducible factor 1 subunit alpha (HIF1α), which reduces vascular endothelial growth factor a (VEGFA) expression, inhibiting cell proliferation." (PMID 39311117, 2024). "In endometrial cancer, AS of vascular endothelial growth factor A (VEGF-A) is regulated by RBM10." (PMID 35836577, 2022). "Since anti-VEGFA, bevacizumab, was widely used for the prevention of various cancers, silence of ZFAS1 might be a promising therapeutic strategy for the prevention of endometrial carcinoma through inhibition of VEGFA." (PMID 34703899, 2021).
endometrial cancer (continued). "Results in this study showed that miR-34b bind to VEGFA in endometrial carcinoma cells." (PMID 34703899, 2021). "pcDNA-mediated over-expression of ZFAS1 attenuated miR-43b mimic-induced decrease in mRNA and protein expression of VEGFA, indicating that ZFAS1 might sponge miR-34b to increase VEGFA in endometrial carcinoma." (PMID 34703899, 2021). "In our study, we verified the roles of miR-299 and miRNA-34a in endometrial cancer progression, the results of dual-luciferase reporter assay show that both two miRNAs could direct regulate VEGFA expression in EC cells." (PMID 28404901, 2017). "Thus mutual relationships in the expression of both HIF1A and EPAS1 and VEGFA but also with other genes and proteins could be of importance also in endometrial cancer progression." (PMID 39888575, 2026). "Therefore, miR-34b might contribute to angiogenesis and progression of endometrial cancer through upregulation of VEGFA, which needs to be further investigated." (PMID 34703899, 2021). "These disturbances presumably alter the VEGFA and PI3K/AKT pathways, leading to uncontrolled cell growth and malignancies, such as small cell lung and endometrial cancers." (PMID 41010006, 2025). "In endometrial carcinoma cells, increased levels of CCL4 meant the upregulation of vascular endothelial growth factor-A (VEGF-A) and tumor growth." (PMID 38928238, 2024). "One of them is to prevent angiogenesis by reducing the concentration of vascular endothelial growth factor A (VEGFA), which has been proven by both in vivo and in vitro studies on endometrial cancer cell lines." (PMID 33530651, 2021). "In endometrial carcinoma, TUG1 enhances the expression of Vascular Endothelial Growth Factor A (VEGFA) by directly binding miR-34a-5p and miR-299." (PMID 32992718, 2020). "In endometrial cancer cells, it has been demonstrated that natural drugs like epigallocatechin gallate (EGCG) decrease the secretion of vascular endothelial growth factor A (VEGFA)." (PMID 40717210, 2025). "Overexpression of lncRNA ABHD11‐AS1 promoted the proliferation, G1‐S progression, invasion and migration of endometrial cancer cells; inhibited apoptosis; up‐regulated cyclin D1, CDK1, CDK2, CDK4, Bcl‐xl and VEGFA; and down‐regulated p16, while ABHD11‐AS1 down‐regulation has the opposite effect." (PMID 29799152, 2018).
liver fibrosis (120 papers, 2007 to 2026). "After establishing bile duct ligation (BDL)-induced liver fibrosis mice model and VEGFA-stimulated LSEC model, we invested the mechanism of SWT through RNA sequencing combined with molecular biology techniques." (PMID 39741334, 2024). "Based on these predictions, we selected PIK3CA, AKT1, HIF1A, VEGFA, and other related targets as the candidate targets of saffron for anti-hepatic fibrosis and conducted further experimental validation." (PMID 37959658, 2023). "In quest for further proof of miR-29b-3p/VEGFA axis being involved in XSSJS-mediated PA alleviation in vivo, we investigated the effectiveness of XSSJS intervention on the expression of miR-29b-3p and VEGFA in liver fibrosis rats." (PMID 35118493, 2022). "Moreover, in rats with liver fibrosis, it can reduce VEGFA, angiotensin I, and transforming growth factor beta 1, as well as the expression of its signal transmission medium, exert antiangiogenic effects by alleviating oxidative stress." (PMID 40550087, 2025). "Resisting angiogenesis in hepatic fibrosis through the PDGFRB/ERK/HIF-1α and VEGFA/AKT/eNOS signaling pathways may serve as a promising therapeutic approach for treating hepatic fibrosis." (PMID 38155904, 2023). "Then, module analysis of the 113 key OGEs was performed using MCODE and the CytoNCA plugin to obtain 6 core genes (CXCL8, MAPK1, AKT1, SRC, VEGFA, and IL-6), which might play important roles in the effects of JQH against WD-associated liver fibrosis." (PMID 35707473, 2022). "Radiotherapy-induced liver fibrosis is often accompanied by angiogenesis, suggesting that VEGFA may play a significant role in RP." (PMID 35509624, 2022). "Furthermore, since it is well known that Vascular Endothelial Growth Factor-a (VEGFA) markedly increases during fibrogenesis and activates multiple downstream signaling pathways promoting the transition from liver fibrosis to HCC, we investigated the effect of OC on its mRNA expression and release." (PMID 34671630, 2021). "RT-PCR and Western blotting analysis confirmed that saffron treatment can prevent the CCl4-induced upregulation of HIF-1α, VEGFA, AKT, and PI3K, suggesting that saffron may regulate AKT/HIF-1α/VEGF and alleviate liver fibrosis." (PMID 37959658, 2023). "PI3K/AKT could also regulate angiogenesis by modulating the expression of angiogenic factors such as nitric oxide and angiopoietins and increasing VEGF/VEGFR signalling and enhanced VEGFA/VEGFR2 signalling in liver fibrosis and angiogenesis." (PMID 37240405, 2023). "In vivo, we observed that oral administration of XSSJS in rats with HF (once a day for 12 weeks) could promote the expression of miR-29b-3p and inhibit the expression of VEGFA, PDGF, and TGF-β in rats with liver fibrosis." (PMID 35118493, 2022). "Therefore, we conclude that miR-29b-3p/VEGFA axis have implications in the role XSSJS played in combating PA of HF, which furnishes us the handle for explaining from the molecular level how XSSJS inhibits PA in the event of liver fibrosis." (PMID 35118493, 2022). "Therefore, Hugan tablets may inhibit the activation of the PI3K-Akt signaling pathway through IL-6, AKT1, VEGFA, EGFR, and MAPK3, thereby inhibiting the activation of HSCs and delaying the occurrence of liver fibrosis." (PMID 34262454, 2021). "MicroRNA-29a (MIR29A) has been shown to exert a hepatoprotective effect on hepatocellular damage and liver fibrosis induced by cholestasis and diet stress, while its clinical and biological role on the activity hypoxia responsive genes including LOX, LOXL2, and VEGFA remains unclear." (PMID 34206143, 2021).
pulmonary fibrosis (115 papers, 2006 to 2025). Chronic progressive interstitial lung disorder characterized by the replacement of the lung tissue by connective tissue, leading to progressive dyspnea, respiratory failure, or right heart failure. "Several clinical studies have documented a reparative effect of VEGFA in the lungs, and it has also been shown that VEGFA has a protective effect against the development of excessive pulmonary fibrosis caused by lung injury." (PMID 37794454, 2023). "Tocilizumab also could reduce the cytokine storm and the subsequent development of oedema and pulmonary fibrosis progression by decreasing VEGFA, IL-4 and especially TFGB1." (PMID 36791125, 2023). "Among those genes, we found that CAV1 and PECAM1 were specifically expressed in lung tissues, BMP4 and VEGFA were related to angiogenesis, FYN and SPP1 were related to immunity or inflammation, and COL1A1 was closely associated with pulmonary fibrosis according to the GeneCards database." (PMID 37794454, 2023). "By searching the 18 candidate hub genes in GeneCards database, we found that CAV1 and PECAM1 were specifically expressed in lung tissues, BMP4 and VEGFA were related to angiogenesis, FYN and SPP1 were related to immunity or inflammation, and COL1A1 was closely associated with pulmonary fibrosis." (PMID 37794454, 2023). "However, it is not clear whether miR‐503 plays a regulatory role by jointly targeting VEGFA and FGFR1 in silica‐induced pulmonary fibrosis and whether there is a synergistic effect between VEGFA and FGFR1." (PMID 33135394, 2020). "Up‐regulated genes include collagen‐degrading matrix metalloproteinase 1 and vascular endothelial growth factor A, which has been shown to be protective against BLM‐induced lung fibrosis." (PMID 38991987, 2024). "The Net-M5 detected genes involved in lung fibrosis (CXCL8 and IL1B), VEGFA-VEGFR2 signaling (NR4A1 and CBL), and TGF-β signaling (JUNB and ATF3)." (PMID 38259488, 2023). "We identified three genes of interest (SPP1, COL1A1, and VEGFA) by bioinformatics analysis that were verified by qPCR in samples of TGF-β1-induced HFL fibroblast cells and pulmonary fibrosis mice." (PMID 37794454, 2023). "Mechanistically, miR‐503 co‐targeted VEGFA and FGFR1, and then blocked the MAPK/ERK pathway, thus alleviating silica‐induced pulmonary fibrosis." (PMID 33135394, 2020). "Combined with the up‐regulation of miR‐503 in a mouse model of silica‐induced pulmonary fibrosis, we revealed that miR‐503 mitigated the TGF‐β1‐induced effects in fibroblasts by regulating VEGFA and FGFR1 and then affecting the MAPK/ERK signalling pathway." (PMID 33135394, 2020). "In conclusion, this study underscores the pivotal role of cellular senescence in the pathogenesis of idiopathic pulmonary fibrosis (IPF) and identifies four key CS-DEGs (CDKN2A, VEGFA, SOX2, and FOXO3) as potential biomarkers for diagnosis and targets for therapy." (PMID 40557159, 2025). "Therefore, we reasoned that miR‐503 negatively regulated the TGF‐β1‐induced effects in fibroblast by co‐targeting VEGFA and FGFR1 to affect the MAPK/ERK pathway, thus alleviating silica‐induced pulmonary fibrosis." (PMID 33135394, 2020).
Insulin resistance (114 papers, 2009 to 2025). Increased resistance towards insulin, that is, diminished effectiveness of insulin in reducing blood glucose levels. "In agreement, blocking ER activity showed decreased VEGFA gene expression, resulting in adipocyte hypertrophy, inflammation, and insulin resistance." (PMID 35721736, 2022). "VEGFA stimulates angiogenesis in adipose tissue,SERPINE4 belongs to pro-inflammatory adipokines, and RBP4 is associated with insulin resistance and visceral fat distribution." (PMID 25887648, 2015). "Increased serum levels of free fatty acids (FFAs) in obese individuals promote vascular endothelial growth factor A (VEGF-A) and vimentin expression through peroxisome proliferator-activated receptor gamma (PPARγ) upregulation, contributing to tumor growth, insulin resistance, and hepatic steatosis." (PMID 38534735, 2024). "It has been shown that targeting angiogenesis by modulating VEGFA levels could influence adipose tissue expansion and metabolic variables such as insulin resistance." (PMID 37219669, 2023). "The findings were confirmed by the induced VEGFA, spliced XBP1, and insulin resistance in Class I obese individuals." (PMID 37219669, 2023). "For example, overexpression of VEGFA within adipocytes or the adipose lineage promotes WAT vascularization to suppress lipid accumulation, inflammation, and HFD-induced insulin resistance." (PMID 35721736, 2022). "Genes with higher degree including VEGFA, PTGS2, JUN, MAPK8, and HSP90AA1 are hub genes of TwHF against DKD, which are involved in inflammation, insulin resistance, and lipid homeostasis." (PMID 33274236, 2020).
Arthritis (111 papers, 2005 to 2025). Inflammation of a joint. "Previous study showed that the dual inhibition of Tie2 and VEGFA reduced disease severity and decreased macrophage infiltration in an animal model of collagen-indued arthritis." (PMID 38015876, 2023). "A cohort study involving patients with ICI-induced arthritis and matched controls revealed significantly elevated serum levels of vascular endothelial growth factor-A (VEGF-A) and TNF-α in the ICI-induced arthritis group, along with increased levels of IFN-γ and IL-6." (PMID 41239350, 2025).